IGF2 (insulin like growth factor 2)
Diseases named in the same sentence as IGF2 in open-access papers (continued):
Sharing a sentence is not in itself a finding about the gene and the disease.
tumor (continued). "We analysed the methylation status of the H19 differentially methylated region (DMR), loss of heterozygosity (LOH) and allelic expression of IGF2 in 54 HB tumours, and found that 12 tumours (22%) with LOH, 9 (17%) with loss of imprinting (LOI) and 33 (61%) with retention of imprinting (ROI)." (PMID 19034281, 2008). "Moreover, expression of IGF-2 protein has been reported to be associated with advanced tumour stage and poor survival." (PMID 15785755, 2005). "Accumulating evidence suggests that enhanced IGF-II expression associated with loss of Igf2 genomic imprinting may promote tumour formation." (PMID 15333144, 2004). "Thus, IGF-2 plays a role as a potential additional diagnostic indicator in these tumor types." (PMID 40270996, 2025). "Moreover, the study detected few associations between IGF-1 and Ki-67, IGF-2, and tumor stage." (PMID 34638601, 2021). "Additionally, the dysregulation of ALDOB and IGF2 caused by hypermethylation and abnormal miRNA regulation through the mediation of miR-21 and miR-29a, respectively, might facilitate tumor metastasis." (PMID 30344796, 2018). "Moreover, a marked IGF2 LOI was found in adjacent tumor-associated tissues as well as in tumor-free distant regions indicating that IGF2 dysregulation could be an early initiation factor in development of prostate neoplasia." (PMID 29017567, 2017). "Thus, high birth weight, one of the manifestations of fetal overgrowth disorder, could be an early marker of the genetic or epigenetic abnormalities present in the IGF2 pathway that increase childhood tumor susceptibility." (PMID 24350186, 2013). "The high number of tumor and growth suppressors defined among the STAT5ca-downregulated genes vs. the potent oncogenes (Met, Igf2) that were induced by the STAT5Δ750 variant may serve to further distinguish the routes via which they initiate and maintain tumorigenesis." (PMID 19450255, 2009). "Igf2 was highly expressed in the Tumor cluster, while the other cell clusters exhibited low expression." (PMID 41568176, 2026). "We identified an amplification of IGF2 and showed that it promotes tumor growth via tumor cell intrinsic and extrinsic mechanisms." (PMID 41568176, 2026). "We identified an amplification of Igf2 in mBT0309, which plays a role in tumor growth and immunosuppression." (PMID 41568176, 2026). "IGF2 offers promise as a valuable therapeutic target to combat tumor growth and immunosuppression in GBM patients." (PMID 41568176, 2026). "Igf1 exhibited low expression compared to Igf2 in the tumor cluster and very low expression in all other clusters, suggesting it had lower importance in this model." (PMID 41568176, 2026). "This paraneoplastic hypoglycemia results from tumor‐derived secretion of high‐molecular‐weight insulin‐like growth factor 2 (IGF‐II)." (PMID 41503433, 2026). "This paracrine effect of IGF2 on CAFs underscores the broader impact of circSMEK1 dysregulation on tumor progression and highlights a potential therapeutic target within TME." (PMID 41103217, 2025). "Another pathway that is implicated in the pathogenesis and progression of CCA is the insulin-like growth factor 2 (IGF2) signaling axis: its role extends beyond tumor growth, influencing metastasis, immune evasion, and therapy resistance." (PMID 41465387, 2025). "A recent systematic review of IGF-2 expression in ACC and benign tissues by IHC revealed various quantitative and qualitative methods for determining IGF-2 positivity in tumor cells." (PMID 40270996, 2025). "Fibroblasts and mesenchymal stromal cells in the tumor stroma secrete cytokines such as HGF and FGF to promote angiogenesis, whereas stromal-related factors such as ISF-1 and IGF-2 promote tumor cell infiltration." (PMID 41281744, 2025). "In WT, alterations in the imprinted genes at 11p15, like H19 and IGF2, can disrupt normal imprinting patterns and lead to the increased expression of IGF2, which can contribute to tumor growth." (PMID 40722750, 2025).
tumor (continued). "IGF2 is overexpressed in tumor cells and myofibroblasts, where it activates the insulin receptor (IR) and IGF1 receptor (IGF1R), promoting cellular survival and proliferation." (PMID 41465387, 2025). "H19 (11p15.5) is located in an imprinted region of chromosome 11 close to the IGF2 gene, and conversely to IGF2, it is expressed only on the maternally inherited chromosome, and its product is a long ncRNA that functions as a tumour suppressor." (PMID 41070359, 2025). "Insulin-like growth factor 2 mRNA-binding protein 3 (IGF2BP3) has been shown to promote cancer progression across various tumor types." (PMID 39883704, 2025). "Oncogenes such as IGF2 also exhibit the hypomethylation of their fetal promoter, leading to their overexpression, which correlates with more aggressive tumor features, including a progenitor-like phenotype and shorter recurrence-free survival." (PMID 40136353, 2025). "The results demonstrated that the IGF2 mainly expressed at CD34+CLDN5+ double positive cells in tumor tissue." (PMID 39674501, 2025). "In response to tumor cell‐derived IGF2, endothelial cells show enhanced motility and proliferation, while inhibition of IGF2 activity impairs LIN28B‐induced angiogenesis in vitro and in vivo." (PMID 40679030, 2025). "In ESCC, CellChat analysis revealed that IGF1 and IGF2, from iCAFs and myCAFs, respectively, were predominant ligands targeting tumor cells." (PMID 41228323, 2025). "It was reported rare cases of NICTH previously, patients have presented with decreased levels of insulin and C‐peptide in the tumor, along with excessive secretion of insulin‐like growth factor‐2 (IGF‐2)." (PMID 40550558, 2025). "We previously showed that IGF2 secreted from oHSV-infected tumor cells reduces therapeutic efficacy and that targeting IGF2 can reprogram the TME to enhance viro-immunotherapy." (PMID 41510300, 2025). "Clinically, elevated IGF2 levels in TNBC tumours has been shown to correlate with adverse prognosis and resistance to anti-PD1 immunotherapy." (PMID 40640495, 2025). "IGF2 also stimulated fibroblast 2 to secrete collagen 1, intensifying tumor malignancy via the collagen 1/integrin α1 signaling pathway." (PMID 40271711, 2025). "Beyond its anti-apoptotic role, IGF2 exhibits cell-type-specific functionalities—driving oxidative phosphorylation in macrophages to resolve inflammation while stabilizing HIF-1α in tumor microenvironments to exacerbate hypoxic stress." (PMID 40722704, 2025). "Many researchers are actively developing small molecule drugs that inhibit the binding of IGF2 to its receptor, thereby blocking the signaling pathways that promote tumor growth and survival." (PMID 39674501, 2025). "It was reported that IGF2 enhanced the migration and growth potential of tumor-derived cells in vitro and in vivo." (PMID 39674501, 2025). "It occurs due to paraneoplastic IGF-2 overproduction by the culprit tumor, which is often incompletely processed IGF-2 (big IGF-2) resulting from aberrant IGF-2 gene expression and precursor processing." (PMID 41179270, 2025). "Consistently, immunofluorescence (IF) staining confirmed the predominant expression of IGF2 in CAFs, whereas Western blot analysis unveiled higher levels of IGF2 protein in CAFs compared with levels in human or murine tumor cell lines." (PMID 39545420, 2024). "Histological staining of tumours is an under‐reported data in studies on IGF‐2‐mediated hypoglycaemia." (PMID 38411039, 2024). "The identification of the C2 IGF2+ tumor cell subtype, in particular, presented a valuable opportunity for future clinical research." (PMID 39896800, 2024). "Tissue samples obtained from responders undergoing anti–CTLA-4 and anti–PD-1 therapy exhibited decreased levels of IGF2 expression within the mammary T11 tumor in comparison with the control group." (PMID 39545420, 2024). "In this case, diffuse and strong IGF2 expression was observed in the tumor cells by immunohistochemistry." (PMID 38982409, 2024).
tumor (continued). "Subsequently, we explored the effects of IGF2 inhibition on both T cell infiltration and tumor progression in syngeneic mouse tumor models." (PMID 39545420, 2024). "During the optimization of IGF-2 antibodies, a high dilution rate was necessary to reduce the basal normal reactivity, which was observed in almost all tumor cells." (PMID 38802933, 2024). "Depletion of IGF2 substantially enhanced oHSV-mediated tumor cell killing in vitro and improved survival of mice bearing BCBM tumors in vivo." (PMID 38853689, 2024). "IGF2 acts to enhance IGF1R signaling within both the tumor and TME cells, supporting tumor regrowth and inducing feedback immunosuppression." (PMID 38853689, 2024). "Using the RCAS/tv-a system to target the expression of SHH, IGF2 and activated Akt to nestin-expressing neural precursors in mice, the researchers found that co-expression of SHH with IGF2 or Akt significantly increased tumour incidence." (PMID 39568072, 2024). "Collectively, these results underscore the crucial role of CAF-derived IGF2 in controlling the immunosuppressive microenvironment and promoting tumor advancement." (PMID 39545420, 2024). "Firstly, aberrant processing of pro‐IGF‐2 in certain tumours leads to increased levels of ‘big’ IGF‐2, which have less efficacy to bind to IGF receptors, thereby potentially lowering the calculated IGF‐2:IGF‐1 ratio." (PMID 38411039, 2024). "The majority of NICTH cases are mediated by insulin-like growth factor 2 (IGF-2), a bioactive polypeptide that is infrequently overexpressed by tumours of mesenchymal or epithelial origin." (PMID 38432069, 2024). "The circle graphs quantified the number and intensity of interactions between all cells with C2 IGF2+ tumor cells as the signal source and fibroblasts as the target respectively." (PMID 39896800, 2024). "Although increasing studies suggest the significant role of elevated IGF2 in tumor malignancy, the focus has mainly been on its direct effects on tumor cells, with its role in TME and tumor immunity still unclear." (PMID 39545420, 2024). "Its pathogenesis is most commonly mediated by tumor overproduction of “big” insulin-like growth factor-2." (PMID 38911593, 2024). "Utilizing the most favorable cut-off point of the IGF2+ tumor cell score, participants in the TCGA dataset were classified into two distinct groups: those with a high ITRS and those with a low ITRS (ITRS referring to the IGF2+ tumor cells risk score)." (PMID 39896800, 2024). "Fibroblasts derived from tumor tissues with elevated levels of IGF2 displayed significant enrichment in specific signaling pathways, such as the PI3K/Akt and chemokine signaling pathways, as well as cytokine-cytokine receptor interaction." (PMID 39545420, 2024). "Through a comparison of the expression levels and regulatory activities of TFs within each module and the tumor cell subtypes, we identified that the TFs in the M2 module predominantly regulated C2 IGF2+ tumor cells." (PMID 39896800, 2024). "In TCGA TNBC cohort, we observed greater enrichment of fibroblasts in the tumor tissues with high levels of IGF2 compared with those with low levels of IGF2." (PMID 39545420, 2024). "In the communication network between C2 IGF2+ tumor cells and fibroblasts, key signaling pathways such as the MK pathway was identified, revealing the complex interactions between tumor cells and stromal cells in the TME." (PMID 39896800, 2024). "A significant increase in IGF2 expression was further confirmed in vivo by ELISA of tumor lysates of intracranial GBM12 or GBM30 tumor-bearing mice treated with rHSVQ when compared to PBS control." (PMID 38853689, 2024). "In this study, we provide robust evidence that oHSV therapy induces the secretion of IGF2, supporting tumor regrowth and maintenance of an immunosuppressive TME following viral clearance." (PMID 38853689, 2024).
tumor (continued). "By conducting a network centrality analysis of the inferred MK signaling network, we discovered that C2 IGF2+ tumor cells function as signal senders, receivers, mediators, and influencers within the MK pathway." (PMID 39896800, 2024). "Non-islet cell tumor hypoglycemia (NICTH) is a rare paraneoplastic syndrome characterized by the release of insulin-like growth factor-2 (IGF-2) and can be instigated by diverse tumor types." (PMID 39219869, 2024). "IGF2R impinges on essential processes in different types of cells, in an opposite way to IGF2; it is thus recognized as a tumor suppressor due to its role in clearing IGF2." (PMID 38612397, 2024). "C2 IGF2+ subtype was a specific type of tumor cells, which exhibited particular gene expression patterns and biological characteristics in tumor cells." (PMID 39896800, 2024). "Our results show a 20-fold increase in INS-IGF2 expression levels in tumor tissues of relapse patients than that of complete remission patients (p value < 0.001), whereas IGF2 expression differs by less than twofold between these groups." (PMID 39593106, 2024). "As the RNA sequencing data suggested induction of apoptosis, inhibition of growth and IGF2-mediated survival as key targets of CM-272, we explored the consequences of CM-272 treatment on the cellular behavior of HB tumor cells." (PMID 38285887, 2024). "In this study, we uncovered the mechanism by which IGF2 reshapes the tumor immune microenvironment via modulation of CAFs." (PMID 39545420, 2024). "It was found that compared with other types of cells, C2 IGF2+ tumor cells had a more significant effect on fibroblasts." (PMID 39896800, 2024). "While SHH alone caused tumours in 15% of the mice, the combination of SHH with IGF2 and Akt increased tumour incidence to 39% and 48%, respectively." (PMID 39568072, 2024). "Fibroblast-derived IGF2 shows a robust correlation with the pattern of T cell exclusion across various tumor types." (PMID 39545420, 2024). "The LOI of IGF2 gene was firstly demonstrated in wilms’ tumor (WT), a renal malignancy of childhood with an embryonic origin." (PMID 38812777, 2024). "oHSV-D11mt treatment secretes IGF2RD11mt locally during active replication, efficiently mitigating the tumor-supportive effects of oHSV-induced IGF2 secretion and greatly enhancing therapeutic efficacy." (PMID 38853689, 2024). "The availability of IGF-1 and IGF-2 to tumor cells from both endocrine sources and autocrine/paracrine production further underscores the importance of this pathway in cancer progression." (PMID 39273251, 2024). "The IGF-1R is activated in at least 50% of BCs, with its natural ligands, IGF-1 and IGF-2, contributing to tumor growth and survival." (PMID 39273251, 2024). "Next, we identified the ligand-receptor signals associated with the communication pathway to determine the primary afferent and efferent signals related to the C2 IGF2+ tumor cells and other cells." (PMID 39896800, 2024). "The results showed that there was a strong intercellular communication network between C2 IGF2+ tumor cells and fibroblasts." (PMID 39896800, 2024). "Using mice with systemic or fibroblast-specific deletion of IGF2, we demonstrated that IGF2 deficiency enhanced the infiltration and cytotoxic activity of CD8+ T cells, leading to a reduction in tumor burden." (PMID 39545420, 2024). "In conclusion, our findings underscored the important role of the C2 IGF2+ tumor cell subtype in HGSOC, particularly its link to advanced disease stages and resistance to therapy." (PMID 39896800, 2024). "To further characterize the tumor cell heterogeneity, we only focused on the clusters 7 and 16, which expressed highest levels of Afp and Igf2 and thus these clusters presumably represent bona fide tumor cells." (PMID 37414763, 2023). "The mechanism of refractory hypoglycemia is related to secretion of insulin-like growth factor 2 (IGF-2) by the tumor." (PMID 36823638, 2023).
tumor (continued). "Another miRNA contributing to the epigenetic regulation of IGF2 in cancer is miR-615-5p, which has been found to bear tumor-suppressing abilities by inhibiting proliferation, migration and invasion in pancreatic ductal adenocarcinoma (PDAC) primary cell lines." (PMID 37371750, 2023). "IGs are considered to be key regulators of embryonic development and global loss of imprinting (LOI) as well as LOI of IGF2, which is regulated by PLAGL1, can lead to tumor formation." (PMID 36437415, 2023). "Two imprinting control regions, one of which is ICR1 that, among other genes, harbors the IGF2 and H19 tumor suppressor genes, were also mapped." (PMID 37810933, 2023). "Another study demonstrated that Id1 increased the expression and secretion of IGF2 in a variety of human cancer types and that targeting IGF2 inhibited growth and metastasis in mice and enhanced tumor chemosensitivity." (PMID 36672737, 2023). "A potential explanation can be found in the contextual and stage-related expression pattern of IGF1 versus IGF2 at the focal tissue level (tumor microenvironment)." (PMID 38255147, 2023). "We observed overall reduction in expression of Cyp2e1 in tumor tissues in comparison with normal livers but marked induction of Igf2, Afp, Dlk1, Epcam and Gpc3 in tumor areas." (PMID 37414763, 2023). "Here, we covered studies that have provided compelling evidence that IGF2 is not only a major factor in primary tumor development, but it also plays a crucial role in cancer spread, immunoevasion, and resistance to therapy." (PMID 36672737, 2023). "IGF2-expressing tumor cells interact with IGF1R-expressing tumor-associated erythroid cells in the patient, and tumor cells expressing SPP1 interact with tumor erythroid cells expressing ITGA4." (PMID 37894821, 2023). "There is evidence that IGFs, namely IGF2, play a role in tumor immunoevasion by regulating the complex immunosuppressive network at multiple levels." (PMID 36672737, 2023). "Since larger tumor is more suspicious about responsible producibility of big IGF2, we planned to resect large ones preferentially and reduce the amounts of residual tumors." (PMID 36742395, 2023). "The critical importance of IGF2 was confirmed by the observation that treatment with an anti-IGFs blocking antibody inhibited in vivo tumor growth derived from a coculture of BC cells and mCAFs injected into mice." (PMID 36672737, 2023). "Given the demonstration by the same study of parallel inhibition of JunB, future studies will have to quantify the role of IGF2 suppression on the whole tumor-suppressing activities of this miRNA." (PMID 37371750, 2023). "The overexpression of the lncRNA Gm15290 exerts tumor-stimulating effects through the inhibition of miR-615-5p, which targets the genes insulin-like growth factor 2 (IGF2), AKT2, and SHMT2." (PMID 37147729, 2023). "ZFP57 has also been previously reported to induce IGF2 expression and subsequently promote the growth of tumor cells." (PMID 37497403, 2023). "These tumors showed enhanced proliferation of CAFs, which determined the IGF2-evoked proliferation of both CAFs and tumor cells." (PMID 36672737, 2023). "Hypoinsulinemic hypoglycaemia characterizes Doege Potter Syndrome (DPS), which leads to an excessive ectopic secretion of insulin-like growth factor 2 (IGF2) by the tumour." (PMID 36769614, 2023). "In transgenic mice that overexpress IGF2 in specific tissues, tumor formation tends to increase in those tissues where IGF2 is overexpressed." (PMID 36971212, 2023). "Specifically, we focus on studies providing compelling evidence that IGF2 is not only a major factor in primary tumor development, but it also plays a crucial role in cancer spread, immune evasion, and resistance to therapies." (PMID 36672737, 2023). "Rather, spontaneous tumor formation was largely restricted to the liver itself, consistent with the other mouse models with tissue‐specific IGF2 overexpression." (PMID 36971212, 2023).